NPY (neuropeptide Y)
Diseases named in the same sentence as NPY in open-access papers (continued):
Sharing a sentence is not in itself a finding about the gene and the disease.
glioma (4 papers, 2022 to 2025). A benign or malignant brain and spinal cord tumor that arises from glial cells (astrocytes, oligodendrocytes, ependymal cells). "[Asn6, Pro34] NPY, a selective ligand of the NPY 1 receptor, ameliorates the therapeutic action of doxorubicin against gliomas, increasing the survival rate." (PMID 39063232, 2024). "Biphalin, an opioid peptide analog, decreases the proliferation of glioma cells, methionine-enkephalin promotes apoptosis in glioma cells, and the ligand of the NPY 1 receptor, [Asn6, Pro34] NPY, increases the survival rate." (PMID 39063232, 2024). "NPY protein expression and NPY release from tumor cells significantly increase in C6 glioma cells after treatment with glutamate." (PMID 39063232, 2024). "This ligand improved blood–brain barrier permeability, targeting glioma cells, and [Asn6, Pro34]-NPY nano micelles also improved the therapeutic effect of doxorubicin against these cells, leading to a high survival rate." (PMID 37373115, 2023). "Finally, glutamate increased the expression of NPY in rat C6 glioma cells, and downregulation of NPY mRNA expression was observed when these cells were implanted into the rat’s third ventricle." (PMID 37373115, 2023).
infarction (4 papers, 2019 to 2025). A localised pathological necrosis of tissue resulting from obstruction of the blood supply usually by a thrombus, an embolus, or vascular torsion. "Myocardial injury and infarction cause sympathetic activation, leading to the release of not only norepinephrine but also the sympathetic co-transmitter NPY." (PMID 41052902, 2025).
injury (4 papers, 2015 to 2023). Damage inflicted on the body as the direct or indirect result of an external force, with or without disruption of structural continuity. "Activating transcription factor 3 (ATF3) is a marker of stress-induced nerve injury, and neuropeptide Y (NPY) is a 36-amino-acid neuropeptide that is significantly upregulated after nerve injury." (PMID 35821338, 2023). "This is the first demonstration of decreased density of CLB, CRT, and NPY in a model of perinatal brain injury." (PMID 30809588, 2019). "Following nerve trauma, a number of neurochemical changes that have been linked to neuropathic pain mechanisms occur within DRG neurons, including the neuronal injury marker activating transcription factor-3 (ATF-3), neuropeptide Y (NPY), galanin and growth-associated protein-43 (GAP-43)." (PMID 25070481, 2015).
knee osteoarthritis (4 papers, 2014 to 2022). "In patients with knee osteoarthritis, concentrations of NPY in synovial fluid were gradually upregulated with the severity of pain, suggesting a role for NPY as a putative regulator of joint homeostasis." (PMID 35273572, 2022).
ovarian carcinoma (4 papers, 2016 to 2022). A malignant neoplasm originating from the surface ovarian epithelium. "It is worthy to note that some of the genes selected by the three methods (e.g., NPY, COL5A1, EGFR, and FBL1) have been already reported in literature where an analysis of subnetwork signatures in ovarian cancer based on Cox model is presented." (PMID 27378931, 2016).
psoriasis (4 papers, 2021 to 2023). An autoimmune condition characterized by red, well-delineated plaques with silvery scales that are usually on the extensor surfaces and scalp. "Based on these findings, it can be speculated that reduced NPY plasma levels in psoriasis patients aggravated mechanical itch by central modulation of this sensation." (PMID 33467067, 2021). "Future studies to determine NPY expression in psoriatic skin relative to uninvolved skin, as well as skin from healthy volunteers, will establish whether NPY may be involved in local psoriasis pathology." (PMID 35418942, 2022). "However, NPY levels in the serum of patients with psoriasis are not different from those of healthy volunteers." (PMID 35418942, 2022).
psychological distress (4 papers, 2017 to 2026). "Previous studies showed that higher levels of blood NPY in response to acute stress predicted better performance during military training, and less psychological distress." (PMID 28231775, 2017).
Sepsis (4 papers, 2013 to 2025). Sepsis is defined as life-threatening organ dysfunction caused by a dysregulated host response to infection. "VIP, together with neuropeptide Y (NPY), suppresses inflammatory mediator release and increases neuronal tolerance to stress factors during the early phase of sepsis." (PMID 40433666, 2025). "As sepsis progresses, however, the sustained increase in NPY leads to metabolic derangements and neurological impairment." (PMID 40433666, 2025). "Exogenous NPY protects against experimental autoimmune encephalitis and decreases inflammation in experimental sepsis." (PMID 23472120, 2013). "NPY has also been shown to play a protective role in shock, sepsis, and autoimmune conditions." (PMID 23472120, 2013). "High-intensity EA at ST36 can activate the spinal sympathetic reflex to inhibit systemic inflammation in sepsis, whereas high-intensity EA at ST25 can activate NPY peripheral sympathetic neurons to exert anti-inflammatory effects." (PMID 37753078, 2023). "Additionally, before the sepsis model was established, high-intensity (3 mA) EA at ST36 or ST25 played an anti-inflammatory role by activating the NPY splenic sympathetic nerve reflex through the spinal sympathetic axis." (PMID 37753078, 2023). "With respect to the beneficial effects of leptin administration during sepsis, it is possible to hypothesize that leptin acts on the excitability of the POMC and NPY/AgRP neurons." (PMID 30618812, 2018).
systemic lupus erythematosus (4 papers, 2010 to 2020). An autoimmune multi-organ disease typically associated with vasculopathy and autoantibody production. "Several reports have demonstrated abnormal concentrations of NPY in systemic lupus erythematosus and RA." (PMID 32377539, 2020). "In systemic lupus erythematosus, sympathetic outflow has been found to be increased as judged from neuropeptide Y (NPY) concentrations in serum." (PMID 22894827, 2012).
amyloid (3 papers, 2022 to 2024). "Intraventricular injection of amyloid in rat reduces NPY mRNA levels in the hippocampus." (PMID 37841892, 2023). "Indeed, hippocampal amyloid injection causes loss of subset of SST INs in CA1 stratum oriens that do no co-express NPY or PV." (PMID 37841892, 2023). "Ishii and Iadecola (2015) reported low plasma leptin levels in Tg2576 mice with low body weight at 3 months of age, before amyloid plaque formation, with the absence of hyperpolarizing responses to leptin in the hypothalamic neuropeptide Y (NPY)." (PMID 35958733, 2022).
arteriosclerosis (3 papers, 2021 to 2023). A vascular disorder characterized by thickening and hardening of the walls of the arteries. "The discovery and complete utilization of NPY functions, including the promotion of EC proliferation and NO secretion, may direct future research and generate hope for the clinical treatment of arteriosclerotic cardiovascular disease." (PMID 33708805, 2021).
Autoimmunity (3 papers, 2015 to 2022). The occurrence of an immune reaction against the organism's own cells or tissues. "Though many of the interactions discussed attribute NPY to causing immune activation and increasing the risk of autoimmunity, many of the features of NPY and its receptors likely play a role in immune homeostasis under normal conditions." (PMID 35418942, 2022). "We investigated the association between the levels of NPY-LA and single nucleotide polymorphisms (SNP) to better understand the genetic regulatory mechanisms of autoimmunity in T1D and the functional impacts of increased NPY-LA levels." (PMID 35627254, 2022). "This was done to better understand the genetic regulatory mechanisms of autoimmunity and the functional impacts of having increased levels of the minor autoantibody, NPY-LA." (PMID 35627254, 2022). "Neuropeptide Y (NPY) is a vesicle cargo peptide, and antibodies against this autoantigen are found in 8–21% of individuals with T1D, but it is still unknown which role it plays in T1D autoimmunity." (PMID 35627254, 2022).
Cerebral ischemia (3 papers, 2021 to 2023). Restriction of arterial blood supply to the brain associated with insufficient oxygenation to support the metabolic requirements of the tissue. "When evaluating the potential pathophysiological role of vasoactive endogenous neuropeptides in sSAH-related cerebral hemodynamic changes, CV-induced cerebral ischemia, and outcome after sSAH, neuropeptide Y (NPY) and calcitonin gene-related peptide (CGRP) have gained paramount interest." (PMID 32572710, 2021). "In this context, NPY was attested a major pathophysiological role in SAH-related cerebral vasospasm (CV) with excessively increased NPY levels in arterial CV and cerebral ischemia." (PMID 38425753, 2023). "Following SAH, NPY was attributed a pivotal role in SAH-induced CV and cerebral ischemia." (PMID 38425753, 2023).
glioblastoma (3 papers, 2024 to 2025). The most malignant astrocytic tumor (WHO grade IV). "NPY increases the level of free intracellular Ca++ and decreases the cAMP (cyclic adenosine monophosphate) level in glioblastoma LN319 cells, which exclusively express the NPY 2 receptor." (PMID 39063232, 2024). "Intratumoral nerve fibers containing NPY have been observed in glioblastomas, suggesting that this peptide, via NPY 2 receptors, modulates the activity of glioblastoma cells." (PMID 39063232, 2024). "The neuropeptide-related genes, including PPY and members of the NPY family (e.g., NPY, NPY1R, NPY2R, NPY4R, NPY5R, PYY), form a distinct cluster characterized by strong co-expression and shared pathway interactions, indicating a potential role in neuroendocrine signaling relevant to glioblastoma." (PMID 40725410, 2025).
Impaired glucose tolerance (3 papers, 2016 to 2022). An abnormal resistance to glucose, i.e., a reduction in the ability to maintain glucose levels in the blood stream within normal limits following oral or intravenous administration of glucose. "NPY overexpression caused impaired glucose tolerance during RD and WD in both genders." (PMID 27681875, 2016).
insulinoma (3 papers, 2023 to 2025). "NPY promoted the growth of exocrine pancreatic carcinoma cells, and the peptide was released from human insulinomas, leading to a high serum NPY level, which returned to a standard level after surgical resection of the tumors." (PMID 37373115, 2023).
meningitis (3 papers, 2019 to 2024). A disorder characterized by acute inflammation of the meninges of the brain and/or spinal cord. "S100B, NSE, and NPY were significantly elevated in the acute miliary tuberculosis with secondary tubercular meningitis vs. other groups." (PMID 33115334, 2021). "In addition, several studies have found that the levels of NSE, S100B, and Neuropeptide Y (NPY) in the serum and cerebrospinal fluid of children with acute miliary TB secondary to TB meningitis are significantly higher than those of children with acute miliary TB or meningitis alone." (PMID 38822291, 2024). "In addition, several studies have found that the levels of NSE, S100B and Neuropeptide Y (NPY) in serum and cerebrospinal fluid of children with acute miliary TB secondary to tuberculous meningitis are significantly higher than those of children with acute miliary TB or meningitis alone." (PMID 31642468, 2019).
metastatic colorectal cancer (3 papers, 2019 to 2023). "NPY gene methylation has been suggested as an early biomarker for metastatic colorectal cancer progression." (PMID 37373115, 2023). "It has also been suggested that plasma NPY methylation analysis would evaluate the clinical benefits of last-line treatment with regorafenib in metastatic colorectal cancer patients." (PMID 37373115, 2023). "NPY gene methylation has been meant to be used as a biomarker for metastatic colorectal cancer progression and for head and neck cancer prognosis and risk." (PMID 37373115, 2023). "We suggest plasma NPY methylation analysis as an easy and universally applicable method for longitudinal monitoring of ctDNA in metastatic colorectal cancer patients." (PMID 31731482, 2019).
neuropathic pain (3 papers, 2022 to 2023). Chronic pain caused by damage to nerve fibers. "Here we show, by selectively activating those cells that continue to express the peptide, that the NPY cells inhibit acute nocifensive reflexes and reduce mechanical and thermal hypersensitivity in both inflammatory and neuropathic pain models." (PMID 37490401, 2023). "Furthermore, NPY-IN activation abolishes mechanical and thermal hypersensitivity in models of inflammatory and neuropathic pain." (PMID 37490401, 2023). "It seemed that the effect of NPY in amygdala in neuropathic pain may be associated with NPY2R, we further explored the regulatory mechanism of NPY2R on MAPK pathway in neuropathic pain." (PMID 35313782, 2022). "The expression of NPY and NPY2R was found to be aberrantly up-regulated in neuropathic pain-related microarray dataset." (PMID 35313782, 2022). "Interestingly, our CPP findings suggest that activating NPY neurons may not suppress on-going pain in the SNI model, implying that on-going and evoked components of neuropathic pain operate through different circuits at the spinal cord level." (PMID 37490401, 2023).
presbycusis (3 papers, 2018 to 2025). Bilateral hearing loss caused by progressive degeneration of cochlear structures and central auditory pathways, typically associated with the aging process. "Our data show increased DCVs in middle and low frequency IC in a model of presbycusis, so it will be interesting to determine whether serotonin or NPY effects change across the tonotopic axis." (PMID 38774486, 2024). "The enhancement of GABA release from NPY-neurogliaform cells and the reversal of the imbalance between excitation and inhibition in the central auditory system following the recovery of cholinergic function may provide an important target for interventions to treat presbycusis with tinnitus." (PMID 29681847, 2018). "Our results suggest that NPY-mediated inhibition in the IC may not be a major contributor to the onset of presbycusis." (PMID 40771198, 2025).
psychosis (3 papers, 2008 to 2023). "Follow up studies have confirmed changes in the expression in Gad1 mRNA, and other GABAergic molecules such as PV, Sst, and NPY, in individuals with psychosis." (PMID 25116473, 2014). "Using a quantitative PCR, we validated a set of genes such as up-regulated metallothioneins (MT1E, MT1F, MT1H, MT1K, MT1X, MT2A and MT3) and down-regulated neuropeptides (SST, TAC1 and NPY) in the dorsolateral prefrontal cortex of psychosis patients." (PMID 18992145, 2008). "We have also confirmed that expression of the neuropeptide genes are down-regulated in psychosis; NPY (p = 0.02, FC -1.32), NR4A2 (p = 0.01, FC -1.39), SST (p = 0.001, FC -1.57) and TAC1 (p = 0.01, FC -1.6)." (PMID 18992145, 2008). "The genes down-regulated in psychosis include neuropeptide genes such as somatostatin (SST), neuropeptide Y (NPY) and tachykinin (TAC1)." (PMID 18992145, 2008).
retinal ischemia (3 papers, 2014 to 2024). A ischemic disease that involves the retina. "However, it is crucial to acknowledge that, in some previous studies, NPY, despite its neuroprotective actions, exacerbated damage in a retinal ischemia injury model." (PMID 39114576, 2024). "NPY pretreatment also prevented NMDA-induced cell death, although in a rat model of retinal ischemia–reperfusion injury pretreatment with NPY could not prevent apoptosis or rescue retinal ganglion cells and retinal function, thus introducing some doubts about NPY’s translational potential." (PMID 31374938, 2019).
sarcopenia (3 papers, 2017 to 2024). Progressive decline in muscle mass due to aging which results in decreased functional capacity of muscles. "ROC analysis indicated that preoperative serum NPY concentration was predictive of having normal HGS before surgery, an SM CSA of ≥92 cm2 in CT slides at L3, and a sarcopenia diagnosis according to the BIA criteria (i.e., percentage of SM < 37% in males and < 31.5% in females)." (PMID 39599612, 2024).
ST Elevation Myocardial Infarction (3 papers, 2018 to 2020). A myocardial infarction that produces elevation in the ST segments of the ECG. "ST-elevation myocardial infarction is associated with high levels of cardiac sympathetic drive and release of the co-transmitter neuropeptide Y (NPY)." (PMID 31834357, 2020). "More recently, we have shown that peripheral venous levels of NPY are significantly elevated in patients undergoing primary percutaneous intervention following ST-elevation myocardial infarction and remain high for at least 48 h." (PMID 30283345, 2018).
stress cardiomyopathy (3 papers, 2018 to 2025). "Finally, it is worth noting that NPY has also been implicated in the pathogenesis of takotsubo syndrome where peripheral venous levels are acutely elevated." (PMID 38847435, 2025). "For comparison, venous NPY levels in patients presenting with Takotsubo cardiomyopathy with severely impaired systolic function and massive catecholamine release were around 186 pg/mL." (PMID 30859228, 2019). "Increased NPY levels have also been specifically found in a rat model of stress cardiomyopathy, as well as in a case report of a patient with stress cardiomyopathy." (PMID 30283345, 2018). "In a mouse model of takotsubo syndrome, there is increased NPY expression in the stellate ganglia." (PMID 38847435, 2025).
ventricular fibrillation (3 papers, 2015 to 2023). A disorder characterized by an electrocardiographic finding of a rapid grossly irregular ventricular rhythm with marked variability in QRS cycle length, morphology, and amplitude. "As part of the symposium presentation, I presented unpublished data suggesting that NPY may play an important role by acting directly on ventricular myocytes to increase susceptibility to ventricular fibrillation." (PMID 25344273, 2015). "Although NPY influences vagal control of heart rate, which in itself could be therapeutically beneficial, our preliminary data suggest that independent of these heart rate changes, cholinergic modulation of ventricular fibrillation (VF) threshold (VFT) remains intact in the presence of NPY." (PMID 25344273, 2015).
vitamin D deficiency (3 papers, 2012 to 2017). A nutritional condition produced by a deficiency of VITAMIN D in the diet, insufficient production of vitamin D in the skin, inadequate absorption of vitamin D from the diet, or abnormal conversion of vitamin D to its bioactive metabolites. "It has been suggested that vitamin D deficiency increases appetite and decreases energy consumption by stimulating Agouti Related Protein/Neuropeptide Y (AgRP/NPY) and suppressing the pro-Opiomelanocortin/Cocaine-Amphetamine-Regulated Transcription (POMC/CART) pathway." (PMID 29281967, 2017). "It is suggested, however, that vitamin D deficiency increases appetite and decreases energy consumption by stimulating Agouti Related Protein/ Neuropeptide Y (AgRP/NPY) and suppressing the pro-Opiomelanocortin/ Cocaine- Amphetamine- Regulated Transcription (POMC/CART) pathway." (PMID 23297844, 2013).
acute coronary syndrome (2 papers, 2019 to 2020). Signs and symptoms related to acute ischemia of the myocardium secondary to coronary artery disease. "Peripheral venous NPY levels were significantly higher in patients with STEMI (n = 45) compared to acute coronary syndromes/stable angina ( n = 48) or with normal coronary arteries (NC, n = 16)." (PMID 30859228, 2019). "NPY levels were compared with 48 patients who were pain-free and undergoing non-emergency coronary angiography for stable angina (SA) or acute coronary syndromes (ACS) and a group of 16 patients undergoing elective coronary angiography who were found to have normal coronary arteries (NC)." (PMID 30859228, 2019).